ID1 (inhibitor of DNA binding 1)
Diseases named in the same sentence as ID1 in open-access papers (continued):
Sharing a sentence is not in itself a finding about the gene and the disease.
breast carcinoma (continued). "The reactivation of the ID proteins, particularly ID1, promotes the development of several tumor types, including high-grade astrocytoma, prostate and breast cancers and non-small cell lung carcinoma." (PMID 24137437, 2013). "A similar peptide aptamer–based approach targeting both Id1 and Id3 (Id1/3-PA7) was shown to induce cell cycle arrest and apoptosis in breast cancer cells MCF7 and MDA-MB-231." (PMID 23342268, 2012). "To further substantiate these findings we aimed to delineate the link between CCND1, ID1 and EMT, as well as clinical properties in primary breast cancer." (PMID 21955753, 2011). "Previously, we have shown that Id1/3-PA7 regulates the expression of CDKN1A and CDKN1B in a dose-dependent manner in breast cancer cells MCF-7 and MDA-MB-231, which contain the homozygous deletions of the gene CDKN2A." (PMID 20842131, 2010). "In parallel, we report that Id-1 is an important target for E6/E7 onco-proteins of HPV type 16, 18, 31, 33 and 35 in breast cancer cells." (PMID 18648363, 2008). "Indeed, DDR1i caused differential expression in several direct RUNX1 target genes including DUT, an essential nucleotide metabolism enzyme seen upregulated across breast cancers, and MYC, along with ANP32B, PLEC, CEBPD, ID1, and STAT3." (PMID 40614729, 2025). "N-α-Acetyltransferase 10 protein (Naa10p), the catalytic subunit of N-acetyltransferase A, inhibits the metastasis of breast cancer cells by binding STAT5A and decreasing STAT5A-stimulated inhibitor of differentiation 1 (ID1) expression in an acetyltransferase-independent manner." (PMID 38124049, 2023). "Finally, we queried the METABRIC breast cancer patient data to examine the correlation between MYC, ZNF148, and ID1/3 expression levels." (PMID 36207293, 2022). "It was reported that in breast cancer cell lines, ID1 induces HIF-1α/VEGFA protein expression but not HIF-1α mRNA expression; in addition, ID1 enhances the stability of the HIF-1α protein." (PMID 35163396, 2022). "In conclusion, ID1 and ID4 may act as biomarkers of tumor aggressiveness and worse prognosis in breast cancer, and they could be used as potential targets for new treatments discover." (PMID 33514024, 2021). "For example, inhibitor of differentiation 1 (Id1) induces MET and stemness in breast cancer cells by antagonizing transcriptional factor Twist1, and transient expression of Twist1 promotes the coexistence of both epithelial and mesenchymal features in the cells." (PMID 31130637, 2019). "Clinical studies have shown that breast cancer patients with negative estrogen receptor status are characterized by high Id1 expression, cell migration and poor prognosis." (PMID 28122577, 2017). "However, the Id1/Id3 aptamer (Id1/3-PA7) has been shown to induce cell cycle arrest and apoptosis in breast cancer cells." (PMID 25693514, 2015). "We also found that the ductal hyperplasia and mammary tumors in MMTV-Id1 mice exhibited expression of the basal markers K5, K14, SMA, and p63, implying the generation of breast tumors with basal marker positivity by Id1." (PMID 25938540, 2015). "We also used a reporter construct consisting of the phospho-SMAD1/5/8 responsive ID1 promoter upstream of a luciferase gene to compare the effects of BMP2 and AB215 treatment on the human breast cancer cell lines MCF7, T47D and SK-BR-3 in the absence or presence of E2 treatment." (PMID 25070479, 2014). "Remarkably, E47 as well as ID1 mRNAs are more frequently expressed in basal-like breast carcinomas compared to non-basal tumours supporting the participation of these proteins in defining this aggressive breast tumour subtype." (PMID 23555842, 2013). "In addition, when Id1 and Id3 are both interfered by Id1/3-PA7, an antiproliferative and apoptotic effect can be observed in breast cancer cells." (PMID 23311395, 2013).
breast carcinoma (continued). "Much like CCND1, some controversy surrounds expression patterns of ID1, and despite numerous links to invasion and migration in breast cancer some groups report an absence of the protein in the normal mammary gland." (PMID 21955753, 2011). "On the other hand, treatment with BMP-2 in the breast cancer cell line C2C12 resulted in increased expression of Id-1, while BMP-2 also positively regulated the expression of Id-1 in certain cell contexts." (PMID 20010941, 2010). "To identify the other potential cellular pathways contributing to TAIII cytotoxicity in tumor cells, we examined the functional role of Id-1 that, along with Id-3 is strongly downregulated in breast cancer cells but not in MCF10A." (PMID 19789631, 2009). "Therefore, the present study clearly suggests that Id-1 is the downstream target of E6/E7 of HPV types 18, 31, 33 and 35 in human breast cancer progression." (PMID 18648363, 2008). "Negative prognostic impacts of increased ID-1 expression have been shown in breast cancers, pancreatic cancers, melanoma, cervical cancers, and ovarian carcinomas." (PMID 19002177, 2008). "On the other hand, Reverse Phase Protein Array (RPPA) data for the breast cancer patient cohort, where it is possible to analyze the change in β-CATENIN protein level, did not include either BMP2/BMP6 or phosphorylated SMADs (SMAD1/SMAD5) or direct target genes of BMP pathway such as ID1–3." (PMID 38731813, 2024). "Therefore, its suppression leads to Id1 induction, which might promote primary tumor vascularization via VEGF production, breast cancer cell invasion and EMT." (PMID 28122577, 2017). "Thus, ID4 may have the opposite function of ID1 and ID2, which are thought to have oncogenic properties in human breast cancer cells." (PMID 18513385, 2008). "Another breast cancer study found a negative prognostic impact of increased ID1 expression." (PMID 16189525, 2005). "It was also shown that inhibiting ID1 and ID3 did not affect breast cancer cells’ capacity to migrate to the lung." (PMID 38195969, 2024). "In HER2/neu negative breast cancer cells, overexpression of MEK1/2-ERK1/2 pathway activators, H-Ras (G12V) and ID-1, also significantly increased the levels of miR-21 so miR-21 expression could be affected by the MEK1/2-ERK1/2 pathway activators independent of HER2 expression." (PMID 32040529, 2020).
lung carcinoma (51 papers, 2010 to 2025). "Specifically, CRTC2 accelerates LKB1-deficient lung cancer progression by stimulating ID1 (inhibitor of DNA binding 1) expression." (PMID 40977688, 2025). "In the present work, we found that trametinib mediated MEK1/2 inhibition downregulates Id1 protein levels in human and murine lung cancer cells, regardless KRAS-mutational status." (PMID 38643157, 2024). "The BMP receptor inhibitor DMH2 caused growth inhibition and cell death in lung cancer cells, but also led to an increase in Id1 expression." (PMID 39578779, 2024). "Overall, these results revealed that the role of cooperation between PGC1α and FOXA1 on the transcription of ID1 is functionally linked to TGFβ1-mediated EMT in lung cancer cells." (PMID 35897813, 2022). "Since ID1 is predominantly expressed in lung cancer among the ID family, we suggest that ID1 serves as an important factor on EMT induced by the loss of FOXA1 and PGC1α." (PMID 35897813, 2022). "Because FOXA1 and PGC1α were found to regulate ID1, ID2, and ID3 in lung cancer cells, we investigated the mechanistic impact of ID1 on the loss of FOXA1-mediated EMT in lung cancer cells." (PMID 35897813, 2022). "This is, to the best of our knowledge, the first report that shows that PGC1α is closely associated with ID1 expression in lung cancer." (PMID 33917757, 2021). "For histology, a low mRNA expression level of ID1 was significantly associated with favorable OS in the following: Adenocarcinoma, squamous cell carcinoma, patients with stage 1 lung cancer, Grade II, AJCC stage N0, sex and smoking history." (PMID 32003423, 2020). "Downregulation of the type I BMP receptors with siRNA or small molecule inhibitors (DMH2, DMH1) in lung cancer cells caused growth inhibition and cell death, which is associated with a down-regulation of Id1 and Id3." (PMID 27048361, 2016). "In a further study we observed a reciprocal association between miR-381 and ID1 in lung cancer cell lines and primary adenocarcinomas." (PMID 26056576, 2014). "Anti-miR-29b enhanced ID1 mRNA and protein levels, and significantly increased lung cancer cell migration and invasion, a hallmark of the Src-ID1 pathway." (PMID 23802096, 2013). "Here we seek to evaluate the expression of Id1 in a pilot study of nonsmall-cell lung cancers (NSCLCs) and determine its diagnostic and functional significance in these tumors." (PMID 20414347, 2010). "In addition, the observation that the stimulation of genes including Id1 by BaP is conserved in human culture cells sets the stage for future attempts to help reduce the risk of smoking-associated lung cancer progression by targeting Id1 in SLE patients." (PMID 37047136, 2023). "The stimulatory effects of BaP on angiogenic and tumorigenic genes including Clec14a, Efnb2, Id1, and Junb were higher in males than in females, which is consistent with the finding that the male sex is a significant risk factor for lung cancer in SLE patients, especially among smokers." (PMID 37047136, 2023). "ID1 is a member of the helix-loop-helix protein family and is expressed in a variety of tumor types; increased expression of ID1 has been shown to be associated with decreased cell differentiation and enhanced cell proliferation, angiogenesis and metastasis of various cancers, including lung cancer." (PMID 25028095, 2014). "Id1-overexpressing H460 lung cancer cells demonstrated elevated expression of cyclin D1 and CDK4 and decreased expression of CDK2, cdc2, and cyclin B1." (PMID 41303422, 2025). "In the KRAS-mutant LUAD setting, Id1 expression, known to provide an aggressive pro-oncogenic phenotype and to enhance the colonization capacity of lung cancer cells, has been shown to correlate with reduced overall survival and poor treatment response." (PMID 38643157, 2024). "Tetramethylpyrazine (TMP) suppressed angiogenesis and tumor growth of lung cancer via blocking the BMP/Smad/Id1 signaling in A549 xenograft in nude mice." (PMID 39578779, 2024).
lung carcinoma (continued). "Id1 gene silencing enhanced PD-L1 expression on lung cancer cells, sensitizing tumor cells to PD-1/PD-L1 axis blockade and enhancing CD8+ T cell infiltration." (PMID 38643157, 2024). "ID1 has also been shown to promote the proliferation, liver metastasis and colonization of lung cancer cells." (PMID 37416767, 2023). "ID1 has been shown to promote migration of lung cancer cells, and FOS was reported to regulate inflammatory response during acute lung injury." (PMID 36762475, 2023). "Id1 downregulation enhanced PD-L1 expression on lung cancer cells surface and increased CD8+ T cell infiltration, sensitizing lung tumors that do not respond to PD-1/PD-L1 mAbs." (PMID 37841258, 2023). "We also observed limitations with [18F]-FDG-PET in our lung cancer murine model when assessing tumor response to PD-1/PD-L1 axis blockade among mice responding to anti-PD-1 blockade and Id1 inhibition." (PMID 37841258, 2023). "By regulating the expression of troponin and shrinking the cytoskeleton to reverse epithelial-mesenchymal transition (EMT), baicalein can inhibit the growth of lung cancer cells through the targeted Src/Id1 pathway." (PMID 36035842, 2022). "In this sense, miR-381 directly targeted ID1 and the reduced miR-381 levels observed in lung cancer cells allows an enhanced ID1 expression, reducing apoptosis and triggering a DDP-resistant phenotype." (PMID 35444536, 2022). "The prognostic value of ID1 was reported in lung cancer and overexpression of ID1 was connected with poor survival of patients with lung adenocarcinoma." (PMID 36101745, 2022). "A549 lung cancer cells exhibit a marked decrease in expression of ID1, a transcriptional target of BMP signaling, whereas ID1 levels are restored on addition of nutrients post-starvation." (PMID 35641992, 2022). "ID1 enhances cell proliferation, colony formation, and tumor growth by regulating the cell cycle in lung cancer." (PMID 34906149, 2021). "To investigate the role of the PGC1α-ID1 axis in human lung cancer on a large scale, we firstly examined PGC1α and ID1 mRNA expressions in 26 different major cancers using TCGA database." (PMID 33917757, 2021). "SMAD1 is best characterized for activating ID1, which promotes proliferation and confers drug resistance in hepatocellular carcinoma, colon cancer, lung cancer, and acute myeloid leukemia." (PMID 34134766, 2021). "Although previous studies support the oncogenic role of ID1, we revealed the cancer-suppressor function of ID1 in lung cancer, which was regulated by PGC1α." (PMID 33917757, 2021). "We found that PGC1α functions as a tumor suppressor of the TCF4-TWIST1-induced EMT transcriptional circuit in lung cancer malignancy via increasing ID1 expression, which can competitively bind to TCF4." (PMID 33917757, 2021). "Collectively, these results indicate that ID1 is required for the EMT process upon PGC1α suppression in lung cancer cells." (PMID 33917757, 2021). "Bioinformatic and clinical studies have shown that PGC1α and ID1 are downregulated in lung cancer, and correlate with a poor survival rate." (PMID 33917757, 2021). "To evaluate the correlation between PGC1α, ID1, and E-cadherin expressions at the protein level, we performed IHC in human lung cancer tissue arrays." (PMID 33917757, 2021). "High ID1 expression is reported significantly correlated with reduced overall survival in lung cancer patients, but the function of ID1 in COVID-19 patients is not known." (PMID 34687295, 2021). "In lung cancer cells, the inhibition of Id1 expression reduces the expression of EMT-related markers (vimentin, intergrin-β, and snail)." (PMID 33936204, 2021). "Among those, one out of three cancers (Lung cancer) consistently showed an altered expression of PGC1α and ID1 throughout databases." (PMID 33917757, 2021). "Tetramethylpyrazine inhibited the growth of lung cancer through disrupting angiogenesis via BMP/Smad/Id-1 signaling pathway." (PMID 32410828, 2020).
lung carcinoma (continued). "A recent study with a novel BMP receptor inhibitor, JL5, has shown the suppression of the expression of Id1 in human lung cancer xenografts." (PMID 33126649, 2020). "Recently, the role of inhibitor of differentiation 1 (Id1) in lung cancer pathogenesis has been gaining interest." (PMID 30949224, 2019). "Genetic loss of Id1 in the host tissue also increased survival and impaired liver colonization of Id1-/- lung cancer mice." (PMID 30949224, 2019). "We show that TAK1 also activates pSmad-1/5 and increases the expression of Id1 in lung cancer cells." (PMID 27048361, 2016). "IHC was used to detect the expression of ID1 in pathological tissues (lung cancer tissues and adjacent tissues)." (PMID 27978873, 2016). "Transient expression of constitutively active BMP and TGFβ type I receptors caused the activation of TAK1 and Id1 expression in the H1299 cells, confirming their role in activating TAK1 in our lung cancer cells." (PMID 27048361, 2016). "Inhibition of BMP receptors with small molecule inhibitors decreases growth and induces death of lung cancer cells, which involves the downregulation of Id1 and Id3 by a Smad dependent mechanism." (PMID 27048361, 2016). "Among the four Id subtypes expressed in primary human malignancies, Id1 has been shown strongly correlated with various types of tumors, including lung cancer." (PMID 25344919, 2014). "It is an upstream regulator of the PI3K/Akt/NFκB pathway in esophageal, head and neck, ovarian, gastric and lung cancer cells, and the expression of vimentin and fibronectin is regulated by Id1 at transcriptional level in NSCLC." (PMID 24970809, 2014). "The expression of Id1 in lung cancer tissues was analyzed by immunohistochemistry, which was then correlated with the clinicopathological characteristics of surgically resected NSCLC patients with definitive adjuvant paclitaxel and cisplatin chemotherapy." (PMID 25344919, 2014). "Our results also provide first evidence that ectopic expression of miR-381 reduced ID1 mRNA and protein levels, and significantly decreased lung cancer cell migration and invasion.." (PMID 26056576, 2014). "We show that the basal BMP activity in lung cancer cell lines is an essential regulator of Id1, Id2, and Id3 expression." (PMID 23593444, 2013). "Our studies suggested a greater role for Id3 in regulating BMP induced cell growth and survival of lung cancer cells than Id1." (PMID 23593444, 2013). "We conclude that Id1 regulates tumor cell migration in NSCLC cells which suggests a functional role in tumor progression for this aggressive form of lung cancer." (PMID 20414347, 2010). "Here we have evaluated the expression of the helix-loop-helix transcription factor, Id1, in human nonsmall cell lung cancers and its functional significance in these tumors." (PMID 20414347, 2010). "In order to explore Id1 protein levels in nonsmall cell lung cancers, a panel of NSCLC cell lines was analyzed for Id1 expression by Western blotting and Id1 transcript level was determined by quantitative RT-PCR." (PMID 20414347, 2010). "A lung cancer study confirmed that Id1 induction was mainly mediated by Akt activation." (PMID 41303422, 2025). "TAK1 further activated pSmad-1/5 and increased Id1 expression in lung cancer cells." (PMID 39578779, 2024). "To understand the physiological relevance related to how decreased PGC1α, FOXA1, and ID1 promote metastasis via EMT in lung cancer, we speculated that TGFβ1, as a major EMT stimulus, could affect the suppression of PGC1α, FOXA1, or ID1." (PMID 35897813, 2022). "Indeed, we found that loss of FOXA1 and PGC1α decreased E-cadherin and increased N-cadherin and vimentin expression, which was significantly reversed by ectopic ID1 expression in A549 lung cancer cells." (PMID 35897813, 2022). "Additionally, baicalein exerted antitumor function through the Src/Id1 pathway in an A549 orthotopic lung cancer model." (PMID 36159573, 2022).